TELO2 (telomere maintenance 2)
Description:
Regulator of the DNA damage response (DDR). Part of the TTT complex that is required to stabilize protein levels of the phosphatidylinositol 3-kinase-related protein kinase (PIKK) family proteins. The TTT complex is involved in the cellular resistance to DNA damage stresses, like ionizing radiation (IR), ultraviolet (UV) and mitomycin C (MMC). Together with the TTT complex and HSP90 may participate in the proper folding of newly synthesized PIKKs. Promotes assembly, stabilizes and maintains the activity of mTORC1 and mTORC2 complexes, which regulate cell growth and survival in response to nutrient and hormonal signals. May be involved in telomere length regulation.
Synonyms: hCLK2; KIAA0683; TEL2; CLK2; YHFS
Tractability: Small molecule: a structure with a bound ligand is known. PROTAC: UniProt records ubiquitination sites on it; ubiquitination databases record sites on it; its protein half-life has been measured.
Gene: Protein-coding gene on chromosome 16 (1,493,329 to 1,510,459, forward strand). Ensembl gene ENSG00000100726.
Subcellular location: Cytoplasm; Membrane; Nucleus; Chromosome, telomere
Subcellular location (Human Protein Atlas): Cytosol; Nuclear bodies
Gene Ontology:
Molecular function: Hsp90 protein binding; kinase binding; protein binding; protein kinase binding; protein-containing complex binding; protein-containing complex stabilizing activity; telomeric DNA binding; molecular adaptor activity
Biological process: protein stabilization; 'de novo' cotranslational protein folding; positive regulation of DNA damage checkpoint
Cellular component: cytoplasm; cytosol; nuclear body; nucleus; TTT Hsp90 cochaperone complex; chromosome, telomeric region; membrane
Genetic constraint (gnomAD): Loss-of-function variants: 71 observed, 84.02 expected, observed/expected ratio (o/e) 0.85, 90% interval 0.7 to 1.03. The synonymous counts are far from expectation, so gnomAD's model fits this gene poorly and the ratio says little. Missense variants: 1,183 observed, 1,102.9 expected, observed/expected ratio (o/e) 1.07, 90% interval 1.02 to 1.12. Synonymous variants: 584 observed, 494.97 expected, observed/expected ratio (o/e) 1.18, 90% interval 1.1 to 1.26.
Gene-disease validity (ClinGen):
ClinGen rates the evidence that TELO2 causes each of these diseases.
TELO2-related intellectual disability-neurodevelopmental disorder (autosomal recessive): Definitive. Disorder characterized by severely delayed global development, microcephaly, abnormal balance and movement.
Homologues: Orthologues: chimpanzee TELO2 (98% identical), macaque TELO2 (91% identical), dog TELO2 (76% identical), pig TELO2 (76% identical), mouse Telo2 (75% identical), rat Telo2 (75% identical), guinea pig TELO2 (67% identical), rabbit TELO2 (66% identical), tropical clawed frog telo2 (50% identical), zebrafish telo2 (44% identical), Caenorhabditis elegans clk-2 (17% identical).
Diseases named in the same sentence as TELO2 in open-access papers:
TELO2 is named in the same sentence as 26 diseases in open-access papers, as found by Europe PMC text mining. Sharing a sentence is not in itself a finding about the gene and the disease. The quoted sentences say what the papers report.
Fanconi anemia (5 papers, 2021 to 2024). Fanconi anemia (FA) is a hereditary DNA repair disorder characterized by progressive pancytopenia with bone marrow failure, variable congenital malformations and predisposition to develop hematological or solid tumors. "Furthermore, TELO2 and SLX4 are enriched in the Fanconi anemia pathway, which is primarily responsible for the repair of DNA strand cross-links, maintenance of genome stability, stabilization of replication forks, and regulation of cell division." (PMID 39457914, 2024). "Among these 14 pathways, four major pathways were enriched: SNARE interactions involved in the vesicular transport (BET1 and STX6), leishmaniasis (FCGR1A, CYBB, and FOS), hematopoietic cell lineages (FCGR1A, ITGA3, MME, and CD5) and Fanconi anemia pathway (SLX4, ATR, and TELO2)." (PMID 37601105, 2023).
colorectal cancer (2 papers, 2021 to 2022). A primary or metastatic malignant neoplasm that affects the colon or rectum. "Using CRISPR-Cas9 genome editing, we fused an auxin-inducible degron (AID) to the endogenous TELO2 or TRRAP proteins in human HCT116 colorectal cancer cells (CRCs)." (PMID 35244540, 2022). "Here, using endogenous auxin-inducible degron alleles, we show that the TTT subunit TELO2 promotes TRRAP assembly into SAGA and TIP60 in human colorectal cancer cells (CRCs)." (PMID 35244540, 2022).
glioblastoma (2 papers, 2016 to 2023). The most malignant astrocytic tumor (WHO grade IV). "In the Annexin-V apoptotic analysis, the apoptotic populations of early and late-stage glioblastomas were reduced in TELO2-silenced GBM8401 cells." (PMID 37298208, 2023). "In contrast, overexpression of TELO2 increased the growth rate of SK-HEP-1 cells through the mechanisms of shortened cell cycle length, and gradually expanded telomere length in human SK-HEP-1 liver adenocarcinoma cell line, suggesting the role of TELO2 for glioblastoma growth." (PMID 27329594, 2016).
glioma (2 papers, 2016 to 2023). A benign or malignant brain and spinal cord tumor that arises from glial cells (astrocytes, oligodendrocytes, ependymal cells). "Our previous study demonstrated that human high-grade gliomas show increased TELO2 mRNA expression and that the overexpression of TELO2 mRNA correlates with shorter survival outcomes, suggesting that TELO2 is an oncogene in human gliomas." (PMID 37298208, 2023). "Telomere maintenance 2 (TELO2) mRNA is highly expressed in high-grade glioma patients, and its expression correlates with shorter survival outcomes." (PMID 37298208, 2023). "Our previous study showed that human high-grade gliomas increase TELO2 mRNA expression and that overexpression of TELO2 mRNA expression correlates with shorter survival outcomes, supporting the finding that TELO2 is an oncogene in human gliomas." (PMID 37298208, 2023). "Our previous study showed that increased TELO2 mRNA expression in human high-grade gliomas correlates with shorter survival outcomes, suggesting that TELO2 is an oncogene in human gliomas." (PMID 37298208, 2023). "This study aims to investigate the correlation between TELO2 mRNA expression and survival outcome of patients with high-grade gliomas." (PMID 27329594, 2016). "The protein level of TELO2 significantly increased correlates with the mTOR expression in human glioma cell lines including U118MG, GBM8401, U87MG, and LN229 as compared with normal brain tissue." (PMID 27329594, 2016). "Taken together, these studies demonstrated the expression of TELO2 correlated with mTOR expression in human gliomas." (PMID 27329594, 2016). "Validation of gene and protein levels, using qRT-PCR, Western blotting, and IHC staining, consistently supports that TELO2 is an oncotarget in human gliomas." (PMID 27329594, 2016). "We further validate the level of TELO2 mRNA expression in human normal brain and three glioma cell lines, LN229, GBM8401, and U118MG through wet lab approach using q-RT PCR." (PMID 27329594, 2016). "To investigate the role of TELO2 in human glioma, we first analyzed the correlation of TELO2 expression with overall survival of human high-grade gliomas." (PMID 27329594, 2016). "The mRNA expression of TELO2 was significantly higher in human LN229 glioma cell line than in normal brain (P < 0.05)." (PMID 27329594, 2016). "The main theme of this study is to clarify the novel role of TELO2 expression in clinical significance of high-grade glioma patients." (PMID 27329594, 2016). "Validation of TELO2 using qRT-PCR, Western blot and immunohistochemical (IHC) staining supports the overexpression of TELO2 mRNA and protein level in high-grade gliomas, implying that TELO2 correlates with adverse outcome in high-grade gliomas." (PMID 27329594, 2016). "Since two dry lab datasets of quantitative gene study supporting the role of TELO2 is oncogene in human high-grade gliomas." (PMID 27329594, 2016). "Investigating TELO2 expression level in GEO dataset revealed higher expression and shorter survival outcome in high-grade gliomas than in low-grade gliomas." (PMID 27329594, 2016). "Consistently, the TELO2 mRNA and protein expression were significantly elevated in human glioma cells in comparison with normal brain control." (PMID 27329594, 2016). "Taken together, human high-grade gliomas increase TELO2 mRNA expression, and overexpression of TELO2 mRNA expression correlates with shorter survival outcome, supporting that TELO2 is an oncotarget in human gliomas." (PMID 27329594, 2016). "Consistently, our data further showed higher expression of TELO2 correlated with the poor survival outcome in high-grade gliomas, supporting the oncogenic role of TELO2." (PMID 27329594, 2016). "Validation using qRT-PCR, Western blotting, and IHC staining further confirmed that TELO2 overexpresses in high-grade gliomas." (PMID 27329594, 2016). "Many studies have revealed that TELO2 might be an oncogenic protein in solid tumors, such as breast cancer and high-grade gliomas." (PMID 37298208, 2023).
glioma (continued). "In conclusion, human high-grade gliomas increase TELO2 mRNA expression." (PMID 27329594, 2016). "The Kaplan-Meier survival curve of 77 patients with high-grade gliomas revealed that patients with low TELO2 mRNA expression levels (n = 56) had longer overall survival than those with high TELO2 mRNA expression levels (n = 21) (P = 0.0017, by log-rank test; 95% CI: 0.1824-0.6735, Ratio 0.3505)." (PMID 27329594, 2016). "Additionally, IHC staining showed higher TELO2 immunostain score in high-grade gliomas than in low-grade gliomas, or normal brain control." (PMID 27329594, 2016). "Finally, the protein production of TELO2 and mTOR in human normal brain and four glioma cell lines, LN229, U87MG, GBM8401, and U118MG through wet lab approach using Western blotting." (PMID 27329594, 2016). "Consistently, these data further support the hypothesis of TELO2 belonging to oncogene in human high-grade gliomas." (PMID 27329594, 2016). "Moreover, TELO2 immunostain score was significant higher in low-grade gliomas than in normal brain (P = 1.54×10−4, P adjusted by Bonferroni method), supporting TELO2 protein overexpressed in high-grade gliomas in comparison with normal brain tissue control." (PMID 27329594, 2016). "The TELO2 immunostain score was significant higher in high-grade (WHO grade III, and IV) gliomas than in low-grade (WHO grade I, and II) gliomas or normal brain (P = 2.19×10−3, 7.53×10−6, respectively)." (PMID 27329594, 2016). "In summary, our findings might provide new insight on the roles of TELO2 in the cell cycle progression, EMT, and drug response of human high-grade glioma cells." (PMID 37298208, 2023). "Moreover, TELO2 was also statistically higher in human GBM8401 and U118MG glioma cell line than in normal brain (P < 0.01, P < 0.005, respectively)." (PMID 27329594, 2016). "Moreover, TELO2 expression was significantly greater in patients with high-grade gliomas than in low-grade gliomas and in those with non-tumor brain controls." (PMID 27329594, 2016). "Moreover, TELO2 level was greater in WHO grade III than in non-tumor controls (p= 0.017) human gliomas." (PMID 27329594, 2016). "However, the correlation of TELO2 with the human gliomas is not yet elucidated." (PMID 27329594, 2016). "However, the role of TELO2 in survival outcome of high-grade gliomas is still not yet clarified." (PMID 27329594, 2016).
microcephaly (2 papers, 2017 to 2019). A congenital or acquired developmental disorder in which the circumference of the head is smaller than normal for the person's age and sex. "Patients with mutations in TELO2 present with microcephaly and associated intellectual disability, postnatal growth retardation and dysmorphic features." (PMID 28944240, 2017).
adenoma (1 paper, 2025). A neoplasm arising from the epithelium. "The study identified mutations in senescence-associated genes, namely, ATM, PIF1, TELO2, XAF1, and RBL1, in five of twenty subjects with multiple adenomas, indicating germline loss-of-function variants in genes that regulate senescence pathways with the development of serrated adenomas." (PMID 40699620, 2025).
Astrocytoma (1 paper, 2023). "The results of the GSEA of Proteins Involved in Astrocytoma were further shown in leading-edge genes in knocked-down TELO2 in GBM8401 cells compared to silencing controls." (PMID 37298208, 2023).
ataxia telangiectasia (1 paper, 2024). Ataxia-telangiectasia is the association of severe combined immunodeficiency (affecting mainly the humoral immune response) with progressive cerebellar ataxia. "TELO2 interacts with members of the phosphoinositide 3-kinase family, such as ataxia telangiectasia mutations, ataxia telangiectasia, and Rad3-associated mutations, and contributes to the regulation of the DNA damage response." (PMID 39457914, 2024).
breast carcinoma (1 paper, 2025). "Additionally, three candidate genes are associated with Breast cancer (DLL3, BRCA2, WNT2B), the mTOR signaling pathway (WNT2B, TELO2, TNFRSF1A), and Pathways in cancer (DLL3, BRCA2, WNT2B)." (PMID 40919429, 2025).
colorectal adenocarcinoma (1 paper, 2022). The most common type of colorectal carcinoma. "Furthermore, TELO2 knockdown with siRNAs resulted in the inhibition of Wnt-induced β-catenin/TCF-dependent transcriptional activation and reduction of the β-catenin level in HEK293 and human colorectal adenocarcinoma (HT-29) cells." (PMID 35530256, 2022).
kidney cancer (1 paper, 2022). Primary or metastatic malignant neoplasm involving the kidney. "This hypothesis is further supported by TELO2 associating with the same component (dMMRICA) in kidney cancer at a more permissive FDR of 2%." (PMID 35764656, 2022).
multiple myeloma (1 paper, 2023). "Surprisingly, TELO2, which encodes Tel2, a well-identified substrate for FBXO9 in multiple myeloma, demonstrated no significance in this analysis." (PMID 38136595, 2023).
otosclerosis (1 paper, 2023). Formation of spongy bone in the labyrinth capsule which can progress toward the stapes (stapedial fixation) or anteriorly toward the cochlea leading to conductive, sensorineural, or mixed hearing loss. "Otosclerosis colocalized genetically with the expression of BANF1, MARK3 and SUPT3H in the highest number of tissues (14, 8 and 6, respectively), while the highest causal posterior probability was observed for TELO2 (9.5%), ZNRD2 (6.3%), EHBP1L1 (6.0%)." (PMID 36653343, 2023).
primordial dwarfism (1 paper, 2017). "This case report serves to (i) add to the clinical delineation of the new YHFS syndrome to include features in keeping with a form of microcephalic primordial dwarfism on the severe end of the clinical spectrum, and to (ii) expand the mutational spectrum of TELO2 to include two novel mutations." (PMID 28944240, 2017).
You-Hoover-Fong syndrome (1 paper, 2021). "Recently, variants of TELO2 have been linked to an intellectual disability disorder, the You-Hoover-Fong syndrome, which could be related to its function in the NMD." (PMID 33444416, 2021). "Recently, mutations in the human TELO2 gene have been linked to the You-Hoover-Fong syndrome." (PMID 33444416, 2021).
cancer (7 papers, 2012 to 2025). A tumor composed of atypical neoplastic, often pleomorphic cells that invade other tissues. "Our findings suggested that the effectiveness of this TELO2-driven therapy should be further confirmed for the functions of TELO2 in normal or cancer cells." (PMID 37298208, 2023). "These transcription factors might facilitate the application of TELO2-targeting drugs in the development of cancer cell vaccines that can prevent cancer recurrence." (PMID 37298208, 2023). "These might facilitate the application of TELO2-targeting drugs in the development of cancer cell vaccines that can prevent cancer recurrence." (PMID 35530256, 2022). "But in addition, we also observed a strong correlation between TELO2 and RAPTOR (in nine out of 10 cancer types), mLST8 (in 10 out of 10 cancer types), mTOR, and RUVBL2 (in five out of 10 cancer types)." (PMID 40653822, 2025).
tumor (3 papers, 2016 to 2023). "TELO2 mRNA expression level was statistically greater in WHO grade IV (n = 81) then in non-tumor controls (n = 23) (P = 2.85 × 10−9)." (PMID 27329594, 2016). "TELO2 mRNA expression significantly higher in World Health Organization (WHO) grade IV than in non-tumor control (p=2.85 × 10−9)." (PMID 27329594, 2016). "Additionally, the significant restraints of the growth, cell cycle, and metastasis of CRC cells manifest after TELO inhibition, indicating that TELO2 promotes tumor progression." (PMID 34064004, 2021). "Moreover, the TELO2 mRNA level was also significantly higher in WHO grade III (n = 19) than in non-tumor controls (P = 0.017, P adjusted by Bonferroni method)." (PMID 27329594, 2016).
neurodegenerative disease (1 paper, 2022). A disorder of the central nervous system characterized by gradual and progressive loss of neural tissue and neurologic function. "Contributes to lysosomal function as well as the viability of neurones; mutations in CLN6 have shown to cause neurodegenerative disease; CLN6 is also associated with mTOR and TELO2 regulators of signaling pathways that are known to be disrupted by ZIKV." (PMID 35371036, 2022).
TELO2 also shares sentences with these, for which no sentence is quoted: developmental delay (2 papers); cervical cancer (1); Intellectual disability (1); leishmaniasis (1); oral cancer (1); Oral Squamous Cell Carcinoma (1); prostate carcinoma (1); viral infection (1).